CD9 (CD9 molecule)
Diseases named in the same sentence as CD9 in open-access papers (continued):
Sharing a sentence is not in itself a finding about the gene and the disease.
neuroblastoma (7 papers, 2007 to 2024). Neuroblastoma (NB) is the most common solid, extracranial childhood tumor. "CD9 upregulation inhibits neuroblastoma metastasis, whilst also associated with favourable prognosis and lack of MYCN amplification." (PMID 38398114, 2024). "We detected low-level CD9 expression in primary neuroblastomas that correlated with metastasized high-risk disease, low probability of patient survival and established clinical and molecular markers for unfavorable disease including MYCN amplification in the tumor." (PMID 27572323, 2016). "Our results show CD9 is a critical and indirectly druggable suppressor of the invasion-metastasis cycle in neuroblastoma." (PMID 27572323, 2016). "High-level CD9 expression in primary neuroblastomas correlated with patient survival and established markers for favorable disease." (PMID 27572323, 2016). "A major factor influencing neuroblastoma biology is the MYCN status in the tumor, which inversely correlated with CD9 expression in primary neuroblastomas." (PMID 27572323, 2016). "Kaplan-Meier analysis showed that high-level CD9 expression in tumors, irregardless of International Neuroblastoma Staging System (INSS) stage or patient age, correlated both with favorable event-free and overall patient survival." (PMID 27572323, 2016). "We investigated CD9 gene methylation status by reanalyzing existing methyl-CpG-binding domain sequencing data from 60 neuroblastomas." (PMID 27572323, 2016). "Combined treatment of neuroblastoma cells with HDAC/DNA methyltransferase inhibitors synergistically induced CD9 expression despite hypoxic, metabolic or cytotoxic stress." (PMID 27572323, 2016). "Our data argue a role for HDAC5 in transcriptionally repressing CD9 in neuroblastoma cells beyond the repression achieved by MYCN and DNA methyltransferases, and offers an avenue for pharmacological intervention." (PMID 27572323, 2016). "High-level CD9 expression in primary neuroblastomas served as an independent favorable prognostic marker." (PMID 27572323, 2016). "CD9 expression diminished with progressive tumor development in the TH-MYCN transgenic mouse model for neuroblastoma, and CD9 expression in neuroblastic tumors was far below that in ganglia from wildtype mice." (PMID 27572323, 2016). "This study identified CD9 as a critical and indirectly druggable node in the neuroblastoma invasion-metastasis cascade." (PMID 27572323, 2016). "Using functional assays, we demonstrated that CD9 suppresses neuroblastoma cell migration and invasion." (PMID 27572323, 2016). "Here we identified GRHL1 as a transcriptional activator of the CD9 gene and showed that MYCN and HDAC5 transcriptionally repress CD9 in neuroblastoma." (PMID 27572323, 2016). "Enforced CD9 expression in neuroblastoma cells transplanted onto chicken chorioallantoic membranes strongly reduced metastasis to embryonic bone marrow." (PMID 27572323, 2016). "Enforced CD9 expression strongly inhibited the number of neuroblastoma cells metastasized to the chicken bone marrow demonstrating that CD9 acts to inhibit the invasion-metastasis cascade in an in vivo neuroblastoma model." (PMID 27572323, 2016). "We next used the TH-MYCN neuroblastoma progression model to analyze the temporal CD9 expression pattern." (PMID 27572323, 2016). "Collectively, our data argue for a role of MYCN in the transcriptional repression of CD9 in neuroblastoma cells." (PMID 27572323, 2016). "Taken together, high-level CD9 expression in primary neuroblastomas signals a favorable tumor biology and patient prognosis independent of established clinical and molecular risk factors." (PMID 27572323, 2016). "Among our cases, CD81 and CD9 showed a variable and heterogeneous pattern of expression with limited utility as individual markers, in the differential diagnosis between neuroblastoma and other pediatric tumors." (PMID 23472067, 2013).
neuroblastoma (continued). "CD9 encodes a tetraspanin protein whose high expression inhibits neuroblastoma development and correlates with a lack of MYCN amplification." (PMID 38398114, 2024). "Interestingly, HDAC5 was also shown to interact with N-myc protooncogene protein (MYCN), and the complex colocalized to the CD9 promoter and attenuated CD9 expression in neuroblastoma cells, leading to tumor cell invasion and metastasis." (PMID 34178647, 2021). "Although CD9 expression could be elevated by either HDAC5 siRNA, or treatment with the HDACi panobinostat, across a number of neuroblastoma cell lines, siRNA mediated knockdown of HDACs 2, 3, and 10 elicited opposing effects on CD9 expression." (PMID 33117806, 2020). "Having shown that CD9 is downstream of GRHL1 in neuroblastoma cells, we assessed whether CD9 is differentially expressed in primary tumors." (PMID 27572323, 2016). "We conclude that GRHL1 activates CD9 transcription in neuroblastoma cells." (PMID 27572323, 2016). "Taken together, CD9 is epigenetically and transcriptionally repressed by the chromatin-modifying enzyme, HDAC5, in association with MYCN, and CD9 expression can be triggered in neuroblastoma cells by inhibition of HDAC5." (PMID 27572323, 2016). "The major strength of CD9 tumor expression as a novel prognostic marker may be its potential for predicting disease progression in neuroblastoma patient subgroups." (PMID 27572323, 2016). "Other less specific markers such as CD56, CD9, CD57, CD81, CD99 also contributed to some differential diagnoses, e.g. the distinction between neuroblastoma and RMS (CD56,CD57,CD81) and between PNET and both RMS (CD9) and neuroblastoma (CD99, CD56, CD81 and CD57)." (PMID 23472067, 2013). "We next used several different neuroblastoma cell and mouse models to investigate the nature of this relationship and the influence of MYCN on CD9 expression." (PMID 27572323, 2016). "Primary neuroblastomas lacking MYCN amplifications displayed differential CD9 promoter methylation in methyl-CpG-binding domain sequencing analyses, and high-level methylation was associated with advanced stage disease, supporting epigenetic regulation." (PMID 27572323, 2016). "Yet, so far, no role for CD9 has been described in neuroblastoma pathogenesis." (PMID 27572323, 2016). "Similarly, several studies have evaluated the utility of CD81 and CD9 (together with CD45− and CD56+), for the discrimination between neuroblastoma cells and BM hematopoietic cells, for staging purposes, without extending such analysis to other subtypes of pediatric solid tumors." (PMID 23472067, 2013).
Sepsis (7 papers, 2018 to 2025). Sepsis is defined as life-threatening organ dysfunction caused by a dysregulated host response to infection. "Sepsis-induced emergency myelopoiesis was associated with significant reductions in the expression of several adhesion molecules (CD11b, CD44, and CD9) on myeloid cells." (PMID 41415274, 2025). "Previous work has also shown that monocytes undergo functional reprogramming during sepsis with a strong bias toward endocytosis, and endocytosis has been shown to abolish CD9 surface expression on cells." (PMID 41415274, 2025). "The EVs expressed typical exosomal (CD63 and CD9) and epithelial (EpCAM) markers, which were further increased by sepsis." (PMID 33182773, 2020). "Expression of the tetraspanins CD63 and CD9 from large intestine lavage EVs was upregulated during sepsis." (PMID 33182773, 2020). "Analysis of transcription factor expression for the DEGs above revealed that Fosl2 and Jdp2, components of the AP‐1 transcription factor complex, were specifically and highly expressed in Hep_Cd9, further supporting its proinflammatory function in response to sepsis." (PMID 37808269, 2023). "Biomarkers of sEVs (CD63, CD9, CD81, Alix, and Tsg101) isolated from healthy control subjects and patients with sepsis were detected using western blotting." (PMID 38910259, 2024). "The analysis of flow cytometry experiments demonstrated that a significant portion of vesicles was positive for CD9 and CD41 in both patients with sepsis and healthy volunteers, suggesting an exosomal and platelet origin for these vesicles." (PMID 29540208, 2018). "Heatmaps revealed that the expression levels of CD63, CD9, CD81, Tsg101, EEA1, Rab5, and Rab7 in lung macrophages were significantly higher than those in neutrophils in the healthy control sEV group and sEVs from patients with sepsis." (PMID 38910259, 2024). "We observed a marked and significant decrease in small CD9+CD14+ and CD9+CD61+ EVs 7 days post-trauma compared with 24-h values in patients who did not develop any post-trauma complications such as systemic inflammatory response syndrome (SIRS), acute respiratory distress syndrome (ARDS), or sepsis." (PMID 38035093, 2023).
small cell lung carcinoma (7 papers, 2012 to 2025). Small cell lung cancer (SCLC) is a highly aggressive malignant neoplasm, accounting for 10-15% of lung cancer cases, characterized byrapid growth, and early metastasis. "CD9 promotes apoptosis in small cell lung cancer cells by positively regulating the expression of calmodulin." (PMID 40860827, 2025). "Previous studies have shown that ectopic expression of CD9 in small cell lung cancer (SCLC) cells represses integrin β1-dependen cell motility and facilitates apoptotic cell death via the inactivation of PI3K/Akt signaling." (PMID 38389703, 2024). "CD9 renders small cell lung cancer cells resistant to cisplatin or etoposide, and increases cell adherence to fibronectin via β1 integrin." (PMID 36941633, 2023). "In small cell lung cancer cell lines, CD9 is highly expressed on cells resistant to cisplatin or etoposide, suggesting that CD9 is a possible marker to indicate treatment resistance." (PMID 24351670, 2013). "CD9 was expressed preferentially in Small cell lung cancer (SCLC) and metastasized tumors." (PMID 22634835, 2012). "CD9 is selectively absent in most small cell lung cancer cell lines and tissues, further leading to a highly malignant phenotype of small cell lung cancer." (PMID 40860827, 2025).
cervical carcinoma (6 papers, 2009 to 2024). A carcinoma arising from either the exocervical squamous epithelium or the endocervical glandular epithelium. "In cervical cancer, CD9 expression is downregulated in the majority of invasive cervical carcinomas, but is locally re-expressed at the site of invasion into blood or lymphatic vessels." (PMID 24520284, 2014). "Therefore, CD9 may be used as an indicator of a high risk of recurrence in cervical cancer." (PMID 24520284, 2014). "In this study, we examined the morphology of exosomes isolated from cervicovaginal lavage specimens of cervical cancer patients by electron microscopy, and measured the expression of exosome-specific markers (CD9 and CD63) by Western blot analysis." (PMID 24406730, 2014). "The microRNA-21 and microRNA-146a levels in the cervicovaginal lavage specimens of cervical cancer patients or control groups were all correlated with the exosomal CD9." (PMID 24406730, 2014). "Similarly, CD9 was down regulated in primary sites of cervical cancers, but re-expressed at sites of trans-endothelial invasion to promote malignant expansion at metastatic sites." (PMID 25762645, 2015).
fibrosarcoma (6 papers, 2013 to 2021). A malignant mesenchymal fibroblastic neoplasm affecting the soft tissue and bone. "In fibrosarcoma cells, podoplanin–CD9 interaction neutralizes podoplanin-mediated platelet aggregation via binding to CLEC-2 and suppresses metastasis." (PMID 33003440, 2020). "CD44 is not the only partner known to interact with podoplanin through the TM region, since tetraspanin CD9, which has four TM domains, was reported to bind podoplanin through TM domains 1 and 2 in fibrosarcoma cells." (PMID 33003440, 2020). "We studied exogenous CD9 expression in human fibrosarcoma (HT1080) cells, a widely used in vitro metastasis model for cell invasion." (PMID 23840773, 2013). "In keratinocytes, down-regulation of CD9 was found to increase activity and expression of MMP9 through JNK signaling, while in a fibrosarcoma cell line, epithelial growth factor receptor, EGFR, was an important intermediary for increased release of pro-MMP9 by CD9." (PMID 25889530, 2015).
lymphoma (6 papers, 2020 to 2025). A malignant (clonal) proliferation of B- lymphocytes or T- lymphocytes which involves the lymph nodes, bone marrow and/or extranodal sites. "The expression levels of p-AKT, CD9, CD63 and PD-L1 in KO + lymphoma group were significantly lower than those in WT + lymphoma group, demonstrating that Notch-1 is a key upstream molecule for the activation of AKT pathway in macrophages." (PMID 38261741, 2024). "Compared with WT group, the expression levels of p-AKT, CD9, CD63 and PD-L1 significantly increased in WT + lymphoma group, suggesting that lymphoma cells can activate the AKT signaling pathway." (PMID 38261741, 2024). "Lymphoma cells enhanced the expression of p-PERK, p-IRE1α, ATF6, IL-6, IL-4, p-AKT, CD9, CD63 and PD-L1 in bone marrow-derived macrophages by mediating the Notch-1 signaling pathway." (PMID 38261741, 2024). "B-lymphoblastic leukemia/lymphoma with ETV6::RUNX1 fusion is often negative for CD9, CD20, and CD66c, and positive for myeloid markers CD13 and CD33." (PMID 40227608, 2025). "B-lymphoblastic leukemia/lymphoma with TCF3::PBX1 fusion is typically strongly positive for CD9, dim-to-negative for CD34, and dim-to-negative for CD20." (PMID 40227608, 2025). "SEVs from representative cases (1 case from lymphoma group and 1 from control group) were positive for CD9 and negative for Cytochrome C whereas the spleen sample had less expression of CD9 and was positive for Cyt-C." (PMID 33230132, 2020). "Moreover, the expression levels of p-AKT, CD9, CD63 and PD-L1 in WT + lymphoma cell + IXA4 group showed little changes compared with WT + lymphoma cell group, further proving that activation of the IRE1/XBP1s signaling pathway by IXA4 does not activate the downstream AKT signaling pathway." (PMID 38261741, 2024). "B-lymphoblastic leukemia/lymphoma with BCR::ABL1 fusion has also been reported to exhibit a decreased expression of CD9 and CD81 when compared with cases of B-lymphoblastic leukemia/lymphoma without cytogenetic alterations or with other cytogenetic abnormalities." (PMID 40227608, 2025). "Our data showed these lymphoma vesicles did not strongly express CD63, LAMP-1, CD9, or TSG101." (PMID 33513976, 2021).
osteosarcoma (6 papers, 2021 to 2025). A usually aggressive malignant bone-forming mesenchymal neoplasm, predominantly affecting adolescents and young adults. "Four transmembrane proteins, CD-9, were detected in the TME of 143 B human osteosarcoma." (PMID 39744442, 2025). "Thus, GD2, CD9, CD105, and CD71 were positive in two osteosarcomas (OS), while CD90 was expressed in only one case, always in the absence of nuMyoD1, numyogenin, CD57, and CD99 expression." (PMID 34638431, 2021).
allergic asthma (5 papers, 2018 to 2024). A asthma with a basis in a pathological type I hypersensitivity reaction. "In the model of allergic asthma, CD9+ B cells play a role in airway inflammation suppression by inhibiting Th2- and Th17-driven inflammation in an IL-10-dependent manner while MZB cells reduce the CD8 T cell function and IFN-γ+ CD4 T cells during the early stages of Leishmania donovani infection." (PMID 34594327, 2021).
Alzheimer disease (5 papers, 2021 to 2023). A progressive, neurodegenerative disease characterized by loss of function and death of nerve cells in several areas of the brain leading to loss of cognitive function such as memory and language. "However, in the TG profiles of serum enriched by CD9 magnetic beads, Alzheimer’s disease and major depression seem to be less abundant than the other three diseases." (PMID 35323673, 2022).
benign prostatic hyperplasia (5 papers, 2017 to 2025). A non-cancerous nodular enlargement of the prostate gland. "The size and the tetraspanin content, in particular CD9, CD81, CD63 and CD41a are different in exosomes collected from benign prostatic hyperplasia, localized PC (LPC) and advanced prostate cancer (AdvPC; 58)." (PMID 34772427, 2021). "PSA, CD9, and gammaglutamyltransferase 1 (GGT1), a cell-surface enzyme, isolated from human serum resulted in significantly higher prostatic cancer (PC) than in benign prostatic hypertrophy (BPH) patients." (PMID 31935918, 2020).
diabetes (5 papers, 2021 to 2025). "CD9, CD63, CD81, and CD41a expression progressively decreased in the Healthy, Diabetes, and DFU groups, respectively." (PMID 39835574, 2025). "Using flow cytometry, we investigated if diabetes alters the relative abundance of CD34+; SCA1+, and CD29High mesenchymal cells in the skin and determined if colocalization with profibrotic markers CD9 and CD26 was different in db/db skin compared to db/+ control skin." (PMID 34944568, 2021).
HIV-1 infection (5 papers, 2009 to 2025). The type species of lentivirus and the etiologic agent of acquired immunodeficiency syndrome (AIDS). "CD9 has been shown to enhance pathogenicity in HIV-1 infection and be involved in cell adhesion and migration." (PMID 33505956, 2020). "Morphological assessment of HCs at day 0 prior to HIV-1 infection revealed a predominance of rounded cells with CD9 in distinct intracellular compartments similar to those found in uninfected MDMs." (PMID 25623930, 2015). "Here we show in HCs on two and six days post-HIV-1 infection, Gag and CD9 displayed strong intracellular colocalization, similar to MDMs, despite the change in morphology." (PMID 25623930, 2015). "To experimentally validate these findings, we assessed whether CD9 surface expression on NK cells was induced by HIV-1 infection and IFN-I signaling by flow cytometry." (PMID 40872811, 2025). "However, a significant inverse correlation was observed between surface CD63 and CD9 in SE and SE-mediated inhibition of HIV-1 infection in a pre-treatment infection model, where increased SE-CD63 or SE-CD9 content is associated with decreased HIV-1 infectivity (f respectively)." (PMID 28338013, 2017). "Our scRNA-seq data revealed that HIV-1 infection increased CD9 expression in NK cells, and cART failed to restore CD9 expression to the baseline levels observed in mock-infected mice." (PMID 40872811, 2025).
lung adenocarcinoma (5 papers, 2014 to 2025). A carcinoma that arises from the lung and is characterized by the presence of malignant glandular epithelial cells. "CD9 was identified as a molecule that suppresses cellular motility and metastatic potential of a human lung adenocarcinoma cell line." (PMID 24466195, 2014). "Lung adenocarcinoma-derived exosomal miR-19b-3p (size range of 100 nm, marker proteins CD9, CD81) and miR-10b (bilayer membrane structure, typical “cupped” structure, marker proteins TSG101,CD63,CD81) facilitate macrophage polarization to the M2 type to promote lung adenocarcinoma development." (PMID 39165926, 2024). "Clinicopathologic findings indicated that CD9 may be a predictor for better prognosis in lung adenocarcinoma." (PMID 24466195, 2014). "Additionally, CD9 expression was linked to improved survival in patients with lung adenocarcinoma, but not in patients with lung squamous cell carcinoma, from the TCGA cohort." (PMID 35493454, 2022). "Then we next isolated serum exosomes from 10 normal controls (NC), 10 interstitial pneumonia patients (IP), 14 lung adenocarcinoma patients (ADC), and 12 lung squamous cell carcinoma patients (SCC) using anti-CD9-MSIA tips." (PMID 25167841, 2014).